BRAF (B-Raf proto-oncogene, serine/threonine kinase)
Diseases named in the same sentence as BRAF in open-access papers (continued):
Sharing a sentence is not in itself a finding about the gene and the disease.
tumor (continued). "In the present study, we investigated the prognostic value of the mutational status of the KRAS, NRAS, PIK3CA and BRAF genes detected in tumor biopsies and plasma samples from 51 synchronous metastatic colorectal cancer (SMCC) patients." (PMID 37176143, 2023). "Here, we validated some previously reported biomarkers such as PD-L1 tumor and immune cells’ expression, and BRAF V600 mutations, in a very heterogeneous population." (PMID 36980349, 2023). "The potential clinical utility of trtDNA analysis is emerged also in colorectal cancer (CRC) where KRAS and BRAF mutation profile detected in urine overlapped with matched tumor tissue and plasma." (PMID 37542343, 2023). "Case 1 underwent a SR through EETA (the tumor harbored the BRAF V600E mutation) and a subsequent adjuvant target therapy with Dobrafenib and Trametinib with a 40% reduction in tumor volume after 2 months and a 90% reduction after 5 months." (PMID 37728836, 2023). "In the case of a multiorgan pattern of relapse, patients were evaluated for the presence of targetable tumor DNA mutations (eg, BRAF, NRAS, and NF1)." (PMID 36852837, 2023). "On a molecular level, BRAF V600E variant lesions were found to have a significantly decreased tumor mutation burden." (PMID 37589977, 2023). "When BRAF mutations occur, the BRAF kinase is constitutively phosphorylated, resulting in tumor development through sustained activation of MAPK pathway signaling." (PMID 37302081, 2023). "Mutations in the BRAF gene, such as BRAF V600E, in advanced stage unresectable or metastaticmelanoma can result in constitutively activated BRAF kinases thatmay stimulate tumor cell growth." (PMID 37037186, 2023). "Very recently, it has been shown that in addition to the high prevalence of BRAF mutation in neoplasia of the lower urinary tract and the prostate of the dog, the BRAF V595E variant is frequent in canine papillary oral squamous cell carcinomas." (PMID 37570213, 2023). "This study also confirms the link between the risk of BRAF mutation and female sex, mucinous histology, high tumour grade, vascular and perineural invasion, and high T and N scores, which is also well documented in the literature." (PMID 37240418, 2023). "BRAF inhibitors appear to reverse some tumor-associated immune-suppressive signals, and the immune-stimulatory effects observed in response to treatments subside with disease progression." (PMID 36673047, 2023). "Our search for a NF-κB signature led to the identification of a transcriptomic signature of tumor progression in BRAF-mutated PTCs." (PMID 37973791, 2023). "Most studies found that the BRAF V600E mutation was more likely to occur in women and in proximal tumours, which is also a finding in the current study." (PMID 37240418, 2023). "BRAF-targeted therapy has set precedence in demonstrating overall and progression-free survival benefits in multiple tumor types harboring the BRAF V600E mutation." (PMID 37231247, 2023). "Mutational status in primary tumours and lymph node metastases agreed in five out of eight, BRAF mutations were discordant in the remaining samples." (PMID 37352166, 2023). "It was less frequently the case for patients with DMG H3-K27M BRAFV600E with only 33% (2/6) tumours where BRAF mutation appeared clonal to H3-K27M mutation." (PMID 38066305, 2023). "The results further indicated that factors such as age, BRAF V600E mutation, tumor size, and calcification independently influence the likelihood of hv-CLNM." (PMID 38012653, 2023). "Overall, this patient with mCRC harboring BRAF V600E mutation responded significantly after receiving triplet mFOLFOXIRI plus bevacizumab chemotherapy regimen, with an optimal response of 70% tumor reduction and achieved a PFS of 13 months." (PMID 37409251, 2023). "Conventional histological tumour staging, BRAF mutations, KRAS mutations, MSI status and TSR were determined." (PMID 37344790, 2023).
tumor (continued). "Drug combinations to simultaneously target multiple pathways/processes are under active evaluation in several BRAF-mutated tumours, and especially in the most aggressive forms, such as anaplastic tumours." (PMID 37198319, 2023). "It showed that the inhibitory activity of apatinib on cell proliferation was concentration-dependent, and it had good inhibitory activity against tumor cell lines with BRAF V600E or RAS mutations." (PMID 36759818, 2023). "Lastly, a study on colorectal cancer stated that high VISTA expression correlated with better disease-free survival (DFS), high tumor infiltrative lymphocyte, microsatellite instability, BRAF mutational status, as well as lower tumor stage." (PMID 37373091, 2023). "and several risk factors have been established, including younger age, larger tumor size, male sex, BRAF V600E mutation, extrathyroidal extension, multifocality, capsular invasion, and microcalcification." (PMID 38012653, 2023). "BRAF mutations are also found in ~10% of colorectal cancers and several other tumor types, but RAF/MEK therapy is rarely effective in these settings." (PMID 36700386, 2023). "These include poor differentiation, a high frequency of BRAF mutations, and a tendency for the primary tumor to be located in the right colon." (PMID 37894457, 2023). "To investigate the association between ARGscore and clinical characteristics, we examined the correlation between ARGscore and age, gender, stage, tumor location, BRAF mutation, and KRAS mutation." (PMID 36909170, 2023). "BRAF V600E mutations are rare events in SCLCs, but the alterations are tumor site-dependent in GEP-NECs and especially enriched in colorectal NECs." (PMID 37422534, 2023). "In contrast, an infiltrating tumor border is significantly more frequent in tumors with activating BRAF-mutations." (PMID 35642343, 2023). "This study provides a reliable tumor tissue-validated home-brew technical basis for the detection of BRAF p.V600E somatic mutations using dPCR in PCM patients." (PMID 37958315, 2023). "BRAF mutations lead to the overexpression of this pathway, which results in uncontrolled tumor growth." (PMID 36849918, 2023). "The RAF kinase family has been reported to be involved in the process of tumor progression, especially BRAF and CRAF, and their mutations lead to a number of outcomes, such as tumor metastasis and apoptosis." (PMID 38133382, 2023). "Combination of oncolytic virotherapy with small molecules targeting the MEK-ERK pathway has also been shown to induce more profound antitumor efficacy than monotherapy in in vivo tumor models with KRAS/BRAF mutations." (PMID 37972012, 2023). "There were found pathological mutations in the primary tumour and also in the patient’s lung metastasis samples in the genes BRAF, namely p.V600E (c.1799 T > C), and FANCA, namely p.S858R (c.2574C > G)." (PMID 37573343, 2023). "LUAD PDO carrying EGFR and BRAF mutations successfully captures the clinical response of the tumor to Dabrafenib/Trametinib combination therapy." (PMID 36696006, 2023). "One of the BRAF mutations, V600E, has been shown to respond well to a combined therapy of dabrafenib and trametinib and has tumor-agnostic regulatory approval." (PMID 37173936, 2023). "BRAF mutations have been associated with 7% of cancers, and there are few published reports of neoplasia in CFC, with only one malignancy." (PMID 38136934, 2023). "This leads to the inactivation of several tumor-suppressor genes and other tumor-related genes, such as mutations in the BRAF gene." (PMID 37108962, 2023). "Sporadic MSI-H CRCs arise via the serrated neoplasia pathway and are strongly associated with BRAF mutations, older age, right-sided tumor location, and high levels of CIMP." (PMID 39132649, 2023).
tumor (continued). "The BRAF-mutated tumours are associated with a right-sided location in the colon and such samples are less likely to be secured by endoscopy." (PMID 37240418, 2023). "We include recommendations for options in unselected patients and therapies that should only be offered in patients with distinct tumor profiles (e.g., BRAF mutations, KRAS G12C mutations, HER2 amplification, deficient MMR, or NTRK gene fusions)." (PMID 38201553, 2023). "Median overall survival (mOS) for metastatic CRC (mCRC) is currently 18–24 months in the unselected population, but it varies according to the RAS and BRAF mutational status and primary tumour side." (PMID 37297026, 2023). "Alternatively, if this correlation is true that BRAF mutated tumours tend to be larger at the time they are biopsied, then their frequent papillary and poorly invasive growth most likely explains the larger size when compared to flat UC." (PMID 37570213, 2023). "The analysis of 3296 conventional PTC patients with tumor size 1–4 cm, treated with total thyroidectomy, revealed that per 10-year age increment, the presence of BRAF mutation, multifocality, and N1b feature were independent factors for bilaterality." (PMID 36775829, 2023). "Tumor mutation analysis showed that gene mutations in the high- and low-risk groups were mainly concentrated in missense mutations of the BRAF gene." (PMID 37025405, 2023). "BRAF inhibition itself is highly desirable given its mutation prevalence and specificity for tumorigenesis in pLGG tumor cells." (PMID 37124503, 2023). "BRAF is a common mutation associated with increased tumor aggressiveness, including higher TNM staging and increased recurrence rates." (PMID 37190300, 2023). "In conclusion, age >45 years, body mass index ≥25, tumor size ≥1 cm, BRAF V600E mutation, and capsular invasion are risk factors for CLNM in patients with PTC." (PMID 38047112, 2023). "Accordingly, during the response to targeted therapy, the BRAF-mutant allele fraction, detectable in the cell-free circulating tumor DNA (ctDNA) at the start of treatment (MAF of 0.64%), became undetectable." (PMID 37569660, 2023). "A bulk mRNA sequencing-based deconvolution analysis was performed to compare the immune profiles of murine tumor models to those of human ATC harbouring BRAF mutation." (PMID 37545523, 2023). "Since the presence of protein activating mutations in KRAS and BRAF genes is very common in PM and tumour grade is a parameter that characterizes tumour cell behaviour, they are probably associated with specific mechanical characteristics." (PMID 37500685, 2023). "Our results show that ZEB1 functions as a tumor suppressor in BRAF-mutant CRCs, highlighting the need to assess the mutational background of CRC before using therapies that inhibit the expression and/or function of ZEB1." (PMID 37870961, 2023). "Nevertheless, we proposed that RNF43 mutation affects the genomic features of BRAF mutant CRC tumours and it can be used as a potential specific marker for future application." (PMID 37409251, 2023). "RAF709 has demonstrated superior antitumor activity in cell line and tumor xenograft models with BRAF or RAS mutations." (PMID 38111008, 2023). "An example was BRAF, whose V600E mutation is highly immunogenic, despite BRAF signalling promoting pro-tumour inflammation." (PMID 37277866, 2023). "Successful modeling was not restricted to one of the most common MAPK alterations of our cohort (BRAF V600E-mutation or KIAA1549:BRAF-fusions), location of the tumor or sex of the patient." (PMID 37999877, 2023). "Based on the preoperative assessment, intermediate-risk PTC, in comparison with low-risk PTC, was associated with age ≥ 45 years, female gender, larger tumor size, and the presence of BRAF mutation or RET/PTC rearrangements." (PMID 36775829, 2023). "Nevertheless, multivariate analysis revealed that BRAF V600E mutation is a poor prognostic factor independent from other prognostic features (age, tumor size, vascular invasion)." (PMID 37547301, 2023).
tumor (continued). "The BRAF V600E-mutated tumor cell has a higher kinase activity compared with the wild type, which promotes proliferation and inhibits apoptosis, finally reducing the sensitivity to patients receiving chemotherapy drugs." (PMID 36759818, 2023). "This study confirmed the well-documented link between the risk of the BRAF mutation and mucinous histology, high tumour grade, and vascular and perineural invasion." (PMID 37240418, 2023). "Both the thyroid subcentimeter PTC and MSO were positive for BRAF V600E mutation, and microRNA expression profiles were similar across all tumor deposits." (PMID 37072862, 2023). "We thus detected the basal and inducible expressions of PD-L1 and MHC class I in these tumor cells with distinct BRAF mutations by flow cytometry and qRT-PCR." (PMID 37853469, 2023). "Our study provides a reliable tumor tissue-validated technical basis for the detection of BRAF p.V600E somatic mutations in PCM patients LB cfDNA." (PMID 37958315, 2023). "As for Case 13’s morphological features, it was a well-circumscribed tumor with pleomorphic cells, necrosis, and a BRAF p.V600E mutation." (PMID 37998600, 2023). "Twenty‐eight validation cohort tumours that had been classified by radiology possessed a consensus clustering classification or detectable BRAF/FGFR1 variant." (PMID 36843390, 2023). "We also assayed our model against eight tumours with weak methylation data that clustered alongside controls by consensus clustering, but where we had detected BRAF/FGFR1 variants by targeted sequencing (seven GG and one DNET)." (PMID 36843390, 2023). "Even for patients with tumours harbouring a BRAF mutation, a resectability rate of 45 per cent and corresponding resection rate of 32 per cent provided at least a chance of prolonged survival." (PMID 36511370, 2023). "Although we did not evaluate if impairing the glycolytic flux induces a switch toward OXPHOS in BRAF-mutated tumour cells, our results encouraged us to exploit energy metabolism as an additional process to target together with the MAPK pathway." (PMID 37198319, 2023). "For the different tumour classes, positive BRAF mutation prediction was associated with tumour regions characterised by papillary growth, a smooth and pushing rather than invasive tumour front, and urothelial differentiation." (PMID 37570213, 2023). "Detection of tumor specific alterations (BRAF-duplication and BRAF V600E-mutation) by digital droplet PCR (ddPCR) at defined time points allowed for determination of tumor cell fraction (TCF) and evaluation of the workflow." (PMID 37999877, 2023). "Patients with BRAF V600E variants were more likely to have larger tumor size, multiple tumors and more vascular/bile duct invasion." (PMID 36867406, 2023). "Despite this, only somatic mutations in BRAF oncogene, as assessed in tumour biopsies, has so far become a validated predictive biomarker of treatment with small molecule inhibitors." (PMID 38201222, 2023). "This tumor is characterized by BRAF p.V600E mutations, that are present in almost all cases, leading to activation of the MAPK/ERK pathway." (PMID 37416813, 2023). "The tumor PTPN11mut/SETBP1mut/TP53hom cell clone exhibited loss of heterozygosity for the BRAF and EZH2 genes, which was consistent with FISH data." (PMID 37684264, 2023). "The clinical and pathological features of 89 patients who had IHC detection of BRAFV600E mutation were also compared between two groups [tumor with BRAF (+) vs. BRAF (−)]." (PMID 36910263, 2023). "It should also be noted that miR-146b deregulation was associated with aggressive tumor behavior in BRAF-positive clinical PTC specimens and that patients with BRAF mutations exhibited increased miR-146b expression in comparison to BRAF wild-type controls." (PMID 37547301, 2023).
tumor (continued). "In light of the recent approval of Dabrafenib-Trametinib therapy in BRAF mutated neoplasms, liquid biopsy would represent an innovative approach that would also facilitate access to this treatment option for many neoplasms." (PMID 37542343, 2023). "Nevertheless, in vivo tumour heterogeneity, intra-tumoral, and intra-patient BRAF mutation have been reported in the primary setting as well as recurrent and/or progressive diseases." (PMID 38201554, 2023). "In our study, we found that in tumor tissue from the BRAF mutant group, TNFRSF1B (encoding TNFR2) was significantly hypomethylated, suggesting potential overexpression of TNFR2 in this group of patients." (PMID 36975440, 2023). "Tumour size ≥20mm, especially in combination with other risk factors such as BRAF and/or TERT mutations or ETE, is an established risk factor for LN metastasis and recurrence." (PMID 37099203, 2023). "BRAFV600E inhibitors, vemurafenib and dabrafenib, showed different activities depending on the patient’s tumor, and in particular, on the BRAF mutation status." (PMID 36624452, 2023). "Although tumor cells re-expressed Nkx2-1 in more advanced tumor stages, it is thus possible that monoallelic loss of Nkx2-1 influences differently BRAF mutant lung and thyroid cells during early tumor development." (PMID 37534159, 2023). "In comparison to patients with a TSR-low/BRAF wt tumour, a BRAF mutation resulted in worse DFS with a HR of 3.66, as did high TSR with a HR of 2.82." (PMID 37344790, 2023). "BRAF inhibitors possess the ability to counteract some of the immune-suppressing effects commonly associated with the BRAF-mutant tumor microenvironment." (PMID 38021761, 2023). "For patients carrying both germline and somatic variants in the BRAF gene, regular monitoring of the tumor is necessary." (PMID 37697378, 2023). "In cohort 1, FFPE tumour biopsies from 127 Danish MM patients, previously analyzed by the Cobas® 4800 BRAF V600 Mutation Test were retrospectively analyzed by the SensiScreen® FFPE BRAF qPCR Simplex and Multiplex assays." (PMID 36758042, 2023). "We have also demonstrated that apatinib can effectively inhibit tumor with BRAF V600E mutation through in vitro and in vivo experiments with promising results." (PMID 36759818, 2023). "Regarding the primary tumor location, our study and other publications have shown that right-sided tumors had a higher rate of BRAF mutations." (PMID 37628868, 2023). "MMR deficiency and BRAF V600E mutation were associated with low tumour necrosis percentage (P = 0.004 and 0 = 0.017, respectively)." (PMID 37031328, 2023). "Mutations of the BRAF protein kinase cause cells to make an abnormal protein that promotes tumor growth." (PMID 37760406, 2023). "Genetic analysis: Detection of the BRAF V600E gene was performed using PCR in paraffin sections of the tumor using the Human BRAF Gene V600E Mutation Detection Kit (Fluorescent PCR Method, AmoyDx, Xiamen, China)." (PMID 37454137, 2023). "Just like NTRK fusions, BRAF V600E mutations are considered tumor-agnostic features predictive to response to BRAF inhibitors." (PMID 37232809, 2023). "In 2015, they suggested that a BRAF mutation prevented tumor progression toward invasive stages and hence was relatively rare in advanced LGSC." (PMID 37600581, 2023). "When the MSI CRC subgroups were compared to each other, only minor differences were found in neutral N-glycan profiles, whereas a clear association between tumor stage and BRAF mutation status was observed in the acidic N-glycan profiles." (PMID 37509233, 2023). "We have demonstrated that apatinib can effectively inhibit tumor cells with BRAF V600E mutation by in vitro and in vivo experiments." (PMID 36759818, 2023). "These tumor-specific factors are often found at advanced/higher stages in patients with BRAF-mutant carcinomas and lower stages in patients with underlying HT." (PMID 37190300, 2023).